TEKT3 (tektin 3)
Description:
Microtubule inner protein (MIP) part of the dynein-decorated doublet microtubules (DMTs) in cilia and flagellar axoneme. Forms filamentous polymers in the walls of ciliary and flagellar microtubules (By similarity). Required for normal sperm mobility (By similarity).
Synonyms: FLJ32828; SPGF81
Tractability: Small molecule: a structure with a bound ligand is known. Antibody: UniProt places it where antibodies can reach, with medium confidence. PROTAC: UniProt records ubiquitination sites on it.
Gene: Protein-coding gene on chromosome 17 (15,303,811 to 15,341,632, reverse strand). Ensembl gene ENSG00000125409.
Subcellular location: Cytoplasm, cytoskeleton, cilium axoneme; Cytoplasm, cytoskeleton, flagellum axoneme; Cytoplasmic vesicle, secretory vesicle, acrosome outer membrane
Subcellular location (Human Protein Atlas): End piece; Mid piece; Principal piece; Calyx; Equatorial segment
Gene Ontology:
Molecular function: protein binding
Biological process: cilium assembly; cilium movement involved in cell motility; flagellated sperm motility; regulation of brood size
Cellular component: axonemal microtubule; extracellular exosome; nucleus; sperm end piece; sperm midpiece; sperm principal piece; acrosomal membrane; acrosomal vesicle; axonemal A tubule inner sheath; microtubule cytoskeleton; sperm flagellum; axoneme; cilium; cytoplasm; outer acrosomal membrane
Genetic constraint (gnomAD): Loss-of-function variants: 43 observed, 46.47 expected, observed/expected ratio (o/e) 0.93, 90% interval 0.72 to 1.19. The upper end of that interval is the gene's LOEUF score, 1.19, which puts it in group 5 of 6, group 1 being the genes least tolerant of losing a copy. Missense variants: 544 observed, 606.32 expected, observed/expected ratio (o/e) 0.9, 90% interval 0.83 to 0.96. Synonymous variants: 201 observed, 226.87 expected, observed/expected ratio (o/e) 0.89, 90% interval 0.79 to 1.
Homologues: Orthologues: chimpanzee TEKT3 (99% identical), macaque TEKT3 (98% identical), dog TEKT3 (92% identical), pig TEKT3 (90% identical), guinea pig TEKT3 (89% identical), mouse Tekt3 (83% identical), rat Tekt3 (83% identical), tropical clawed frog tekt3 (71% identical), zebrafish tekt3 (63% identical), Drosophila melanogaster CG17450 (38% identical), Drosophila melanogaster CG32819 (38% identical), Drosophila melanogaster CG32820 (38% identical). Paralogues in human: TEKT5 (49% identical), TEKT4 (34% identical), TEKT1 (30% identical), TEKT2 (25% identical), MAFIP (10% identical).
Diseases named in the same sentence as TEKT3 in open-access papers:
TEKT3 is named in the same sentence as 11 diseases in open-access papers, as found by Europe PMC text mining. Sharing a sentence is not in itself a finding about the gene and the disease. The quoted sentences say what the papers report.
asthenozoospermia (3 papers, 2020 to 2024). "We have previously reported on genes whose KO led to asthenozoospermia, such as Tektin 3 (TEKT3), Tektin 4 (TEKT4), T-complex-associated-testis-expressed 1 (TCTE1), and T-complex 11 (TCP11), with each having unique roles in sperm motility." (PMID 32588889, 2020). "Furthermore, two homozygous TEKT3 mutations have been recently identified in infertile men with asthenospermia, highlighting the relevance of tektins deficiency to human male infertility." (PMID 38448737, 2024). "Tekt3-null mice produce spermatozoa with reduced progressive motility and increased structural bending defects of the flagellum, suggesting that Tekt3 might be involved in idiopathic asthenozoospermia in humans." (PMID 35804605, 2022).
infertile (2 papers, 2024). "A recent study identified two homozygous TEKT3 mutations in infertile men with oligo-astheno-teratozoospermia, highlighting the relevance of tektins deficiency to male infertility." (PMID 38448737, 2024). "These efforts have revealed that genes such as TEKT3 may be important causes of male infertility in the general population, even though their knockout in mice does not lead to infertility." (PMID 38563001, 2024).
male infertility (2 papers, 2024). The inability of the male to effect fertilization of an ovum after a specified period of unprotected intercourse. "Tekt3−/− mice produce sperm with reduced motility and increased flagellar structural beading defects but not male infertility." (PMID 38448737, 2024).
asthma (1 paper, 2020). "Among ten hub DEGs identified for the asthma-COPD, nine DEGs including SPAG6, C7orf57, SYTL3, LRRC48, TEKT3, CCDC146, CETN2, CCDC19, and C14orf45 were identified as the novel genes." (PMID 31952466, 2020).
hearing loss (1 paper, 2025). "However, zebrafish saccular HCs and mouse cochlear inner HCs, the true sound sensor cells in both animals, both lack the protein, suggesting less relevance of TEKT3 to hearing loss disease of humans." (PMID 40243732, 2025).
liver cancer (1 paper, 2023). An epithelial or non-epithelial malignant neoplasm that arises from the liver. "Moreover, the mutations in CNTN5 were reported to contribute to the metastatic process of pancreatic cancer, HTR4 was found predominantly in only high-grade prostate cancer, and the high expression of TEKT3 could be influenced by HBV integration events in liver cancer." (PMID 36816541, 2023).
TEKT3 also shares sentences with these, for which no sentence is quoted: breast carcinoma (1 paper); female infertility (1); pancreatic cancer (1); prostate carcinoma (1); tumor (1).